COL6A1 (collagen type VI alpha 1 chain)
Diseases named in the same sentence as COL6A1 in open-access papers (continued):
Sharing a sentence is not in itself a finding about the gene and the disease.
myopathies (continued). "Regarding COL6-related myopathies, these approaches were shown to be beneficial both in preclinical studies in Col6a1–/– mice and in a pilot clinical trial in UCMD and BM patients, in which autophagy was successfully promoted through a 1-year-long low protein diet." (PMID 33134297, 2020). "In skeletal muscles of col6a1 null mice, the impairment of autophagosome formation triggers the accumulation of dysfunctional mitochondria and aberrant organelles in myofibers, leading to myofiber apoptosis and myopathy." (PMID 27656840, 2016). "In previous studies aimed at mechanistic insight into the autophagic defects of COL6-related myopathies, we have demonstrated that col6a1−/− muscles display a hyperactivation of the AKT-MTOR pathway and that this signaling defect plays a key role in the autophagy impairment." (PMID 26565691, 2015). "We have previously found that persistence of dysfunctional organelles due to autophagy failure is a key event in the pathogenesis of COL6/collagen VI-related myopathies, and have demonstrated that reactivation of a proper autophagic flux rescues the muscle defects of Col6a1-null (col6a1−/−) mice." (PMID 26565691, 2015). "These mice represent a valuable model for investigating the pathogenic mechanisms of collagen VI diseases at the molecular level and studies on Col6a1 null mice revealed that mitochondrial dysfunction and defective autophagy are involved in the pathogenesis of collagen VI myopathies." (PMID 25158062, 2014). "Although the link between altered ECM and muscle fiber degeneration is not yet completely understood, the generation of a mutant mouse with targeted inactivation of the Col6a1 gene (Col6a1−/−) provided a valuable tool for a better understanding of the pathophysiology of collagen VI myopathies." (PMID 23437220, 2013). "Given the myopathy of Col6a1−/− mice, abnormal loading may be present at the knee and could influence trabecular bone characteristics." (PMID 22448243, 2012). "Although the gold standard for the diagnosis of collagen VI myopathy is sequencing of the COL6A1, COL6A2 and COL6A3 genes, this technique is complicated by both the large size of the three genes (107 coding exons in total) and the high frequency of polymorphisms." (PMID 22075033, 2012). "Considering that defective regulation of autophagy plays a key role in the muscle pathology of both Col6a1–/– mice and patients affected by COL6-related myopathies, and that its reactivation leads to beneficial effects, we investigated the effects elicited by Pt administration to Col6a1–/– mice." (PMID 33134297, 2020). "Our first diagnostic hypothesis was either myopathy or collagen VI pathology, but molecular analysis of the COL6A1, COL6A2, COLA613, RAPSN genes did not reveal any rare or pathogenic variant." (PMID 31614862, 2019). "In Col6a1–/– mice, the best-characterized animal model of COL6-related myopathies, defective regulation of the autophagic process leads to the accumulation of dysfunctional and harmful organelles, which dramatically affects myofiber viability." (PMID 33134297, 2020). "Taken together, these results demonstrate that UCMD and BM melanocytes display the same PTP-dependent latent mitochondrial dysfunction previously identified in primary muscle-derived cell cultures from Col6a1−/− mice, UCMD and BM patients, and zebrafish with ColVI myopathy." (PMID 25477819, 2014).
connective tissue disorder (6 papers, 2020 to 2025). A disease involving the connective tissue. "Human studies on connective tissue disorders, such as those associated with COL6A1 mutations, suggest that similar mechanisms may also apply to dogs with PL." (PMID 41463830, 2025). "Analysis of genes causing connective tissue disorders according to ACGS guidelines revealed four P/LP variants in COL1A1, COL6A1, FKBP14, and ALPL." (PMID 39298385, 2024). "Noteworthy, the mutations in COL5A1, COL6A1, or COL12A1 cause connective tissue disorders in humans, altering fiber organization and mechanical properties, resulting in tissue fragility." (PMID 34575162, 2021).
neuromuscular disease (4 papers, 2020 to 2025). "Additionally, the MRI results indicated that the COL6A1 variant might explain the manifestation of a neuromuscular disease in this patient." (PMID 37047781, 2023).
infection (3 papers, 2015 to 2024). The state of being infected such as from the introduction of a foreign agent such as serum, vaccine, antigenic substance or organism. "COL6A2, localized in the ECM, was detected at all three E. granulosus infection stages; COL6A1 expression increased significantly in the middle and late infection stages." (PMID 39625960, 2024). "It includes genes related to collagen production and organization (COL6A3, COL6A2, COL6A1, etc.), or matrix metalloproteinases (MMP) involved in extracellular matrix remodelling (MMP7, MMP23B), and previously implicated in infection response." (PMID 26331304, 2015). "However, BLOC1S1, SCARA3, COL6A1, and HGSNAT were unaffected by HCoV-OC43, suggesting that IRE1α activity is limited to XBP1 splicing during infection." (PMID 37306512, 2023). "The involvement of COL6A1 expression in ECM development around the lesion, as well as its immunosuppressive effect, may explain the reason that clinical symptoms do not appear in patients with CE until several years after infection." (PMID 39625960, 2024).
muscular disorders (1 paper, 2023). "Although our three patients with COL6A1-associated muscular disorders (Patients MD1-MD3) were found to harbor only one variant, there is a possibility that they are actually compound heterozygous with the other variant not identified by our methods." (PMID 36697461, 2023).
uterus (1 paper, 2017). "The data obtained in Antxr2−/−::Col6a1−/− mice indicates that collagen VI is the key initiator of the uterus fibrosis and most likely of nodule formation in humans." (PMID 28604699, 2017).
COL6A1 also shares sentences with these, for which no sentence is quoted: autoimmune disorders (2 papers); congenital myasthenic syndrome (2); congenital myopathies (2); Duchenne muscular dystrophy (2); gastric cancer (2); genetic disease (2); Hypertension (2); keratosis pilaris (2); renal cell carcinoma (2); Stickler syndrome (2); Abdominal obesity (1); acute myocardial infarction (1); adenocarcinoma (1); ameloblastoma (1); aortic valve calcification (1); atrial septal defect (1); breast invasive carcinoma (1); cardiomyopathy (1); Central core disease (1); cervical squamous cell carcinoma (1); channelopathies (1); collagenopathies (1); colonic adenomas (1); congenital heart disease (1); corneal dystrophies (1); deafness (1); dilated cardiomyopathy (1); distal myopathy (1); Emery-Dreifuss muscular dystrophy (1); endometrial cancer (1).
A further 47 diseases each share a sentence with COL6A1 in 1 paper.